KIT (KIT proto-oncogene, receptor tyrosine kinase)
Diseases named in the same sentence as KIT in open-access papers (continued):
Sharing a sentence is not in itself a finding about the gene and the disease.
mastocytosis (continued). "Thus, the type and severity of mastocytosis symptoms appears to be unrelated to the presence of the D816V KIT mutation." (PMID 18509466, 2008). "We hypothesized that point mutations in exon 17 of the c-KIT proto-oncogene, similar to those seen in human patients with mastocytosis, are responsible for the aberrant KIT localization in MCTs without ITD c-KIT mutations." (PMID 16579858, 2006). "The diagnosis of mastocytosis is based on the World Health Organization criteria, which include elevated serum tryptase levels, histopathological and immunophenotypic evaluation of mast cells, and molecular analysis for KIT mutations, particularly the D816V mutation." (PMID 40546465, 2025). "However, patients with mastocytosis and HαT appear to present with features of lower mast cell burden, such as lower KIT D816 V variant allele frequency (VAF) in blood, bone marrow (BM) aspirates or BM biopsies, lower BM cell infiltration, and fewer BM MC clusters, even within subgroups of SM." (PMID 40612891, 2025). "Earlier studies have reported an association between mastocytosis and MM, findings that have been hypothesized to reflect common pathogenesis including a potential role of growth-promoting cytokines produced by MCs and co-occurrence of KIT mutations." (PMID 40824156, 2025). "Furthermore, mastocytosis is a disease where MCs can become transformed and may express mutant proteins, such as the tyrosine kinase receptor KIT, whose mutations produce a constitutively active protein." (PMID 40362499, 2025). "Activating KIT mutations are associated with mastocytosis, but it remains currently undetermined whether individual mutations are both necessary and sufficient to cause aberrant mast cells and the various clinical manifestations of mastocytosis." (PMID 37762215, 2023). "Besides MC, eosinophils and basophils are those subsets of leukocytes that most frequently carry the KIT mutation in mastocytosis patients presenting with multilineage involvement of hematopoietic cells, in association with partial expression of CD117 in the later cells." (PMID 35344302, 2022). "Although KIT mutations, particularly KIT D816V, have been considered as a key mutation for mastocytosis, however, increased body of data indicates that KIT D816V may be a late event in the pathogenesis of mastocytosis and other alterations/mutations may be involved as early events." (PMID 29088753, 2017). "As gain of function mutations in KIT are present in 90% of adult mastocytosis patients and mutations in tyrosine kinase oncogenes can cause ROS accumulation, we examined whether mast cells carrying KIT mutations have abnormal ROS and DJ-1 levels reminiscent of patients with SM." (PMID 27611333, 2016). "Because DJ-1 is linked to mast cell activity, oxidative regulation and cancer progression, we thus investigated whether DJ-1 is dysregulated in mastocytosis in association with disease severity and in a model of mastocytosis, as well as the possible impact of KIT mutations on DJ-1 and ROS levels." (PMID 27611333, 2016). "Additionally, in order to determine if mutations in exon 17 of c-KIT, where the majority of mutations occur in human mastocytosis patients, were responsible for aberrant KIT localization, exon 17 was screened in 18 MCTs with aberrant KIT localization that lack ITD c-KIT mutations." (PMID 16579858, 2006). "More selective and potent KIT inhibitors are now available, including avapritinib, which is currently approved for the treatment of advanced systemic mastocytosis based on the results of the PATHFINDER and EXPLORER trials." (PMID 40576687, 2025).
mastocytosis (continued). "Midostaurin, a multikinase/KIT inhibitor, is approved for the treatment of advanced systemic mastocytosis (AdvSM)." (PMID 40781766, 2025). "The presence of a KIT mutation (D816V, in most adults patients) and/or a phenotypically abnormal MCs population are the hallmarks of primary MCAS, mastocytosis and its subcategories according to WHO 2022 classification." (PMID 39877259, 2025). "This case underscores the intricacies of managing a patient with advanced systemic mastocytosis, the emerging role of highly selective KIT inhibition in its treatment, and the practical management of adverse medication effects." (PMID 38868249, 2024). "In a French population of children with mastocytosis, 3 of 610 patients had congenital ASM with the KIT D816V mutation, and all of them presented with skin lesions corresponding to DCM." (PMID 38338679, 2024). "Nevertheless, mastocytosis’s clinical and molecular heterogeneity requires studies beyond KIT approaches." (PMID 36834926, 2023). "MITF expression is regulated by KIT-dependent signals and is required for the transformed phenotype of mastocytosis." (PMID 36834926, 2023). "C-KIT is a recognized proto-oncogene that has been identified in GIST, acute myelogenous leukemia (AML) and mastocytosis and the KIT protein is the target of clinical tyrosine kinase inhibitors such as imatinib." (PMID 36970068, 2023). "The NHS Genomics Service in the UK has extended germline testing criteria for KIT and other GIST predisposition genes to affected patients before the age of 50 years if they have associated mastocytosis, family history of GIST or associated cancers." (PMID 37311038, 2023). "Of note, HHT has also shown preclinical activity in KIT D816V-mutant mastocytosis models, a disease that is intrinsically resistant to imatinib and most other TKIs targeting KIT31." (PMID 35585158, 2022). "HHT has also shown activity in KIT-mutant mastocytosis models, which are intrinsically resistant to imatinib and most other TKIs." (PMID 35585158, 2022). "Mastocytosis is a KIT‐related myeloproliferative disease characterised by abnormal expansion of neoplastic mast cells (MC) in the skin or virtually any other organ system." (PMID 35876458, 2022). "HuMC‐derived EVs can transfer KIT to other cell types altering the recipient cell phenotypes and potentially contributing to the pathogenesis of mastocytosis." (PMID 36239715, 2022). "In the UK, NHS Genomic Services has expanded the criteria for germline testing of KIT and other GIST predisposition genes to patients affected before age 50 years, if there is associated mastocytosis, a family history of GIST or associated cancers." (PMID 35791894, 2022). "We assessed clinical, demographic, and laboratory data, including mastocytosis activity score (MAS), serum tryptase, and KIT D816V allele burden." (PMID 35958589, 2022). "Unlike other hematopoietic cells, mast cells express many KIT receptors that remain responsive to SCF, so mutations in KIT or dysregulation of SCF lead to uncontrolled mast cell proliferation, and mastocytosis occurs." (PMID 34680251, 2021). "KIT mutational status has been determined only in a few cases of MCL and MCS in adults with a previous history of pediatric mastocytosis." (PMID 33806685, 2021). "These variants are often found in pediatric mastocytosis and are typically located in the extracellular domain (ECD) encoded by exons 2, 8 and 9 of the KIT gene." (PMID 33401724, 2021). "In mastocytosis, KIT is constitutively activated, which leads to persistent downstream activation signaling." (PMID 32346366, 2020). "Beyond the outstanding results obtained in CML, imatinib also showed activity against other TKs such as PDGFR and KIT, which led to explore its efficacy in diseases driven by genetic alterations in these receptors including mastocytosis." (PMID 32346366, 2020).
mastocytosis (continued). "The development of KIT-blocking tyrosine kinase inhibitors has increased overall survival rates among patients with aggressive forms of mastocytosis and has improved quality of life for patients with indolent forms of the disease." (PMID 31824655, 2019). "Recently, signaling molecules involved in KIT signaling have been gaining attention as possible therapeutic targets for mastocytosis." (PMID 28725969, 2018). "It has to be noted, that IC50s in the mutant-KIT D816 mastocytosis cell lines in response to crenolanib are ∼100-fold less sensitive compared to (FLT3 ITD+) MOLM14 cells." (PMID 29137311, 2017). "Gain‐of‐function mutations in KIT have been linked to myeloproliferative disorders, for example, acute myeloid leukemia (AML) and neoplastic mast cell (mastocytosis)." (PMID 28332308, 2017). "Two reference cell lines, Ba/F3 KIT D816V and (KIT D816V positive) HMC1.2 mastocytosis cells were cultured in this medium for 48 hours to address induction of apoptosis using an annexin V-based flow cytometry assay." (PMID 29137311, 2017). "Here we demonstrate that crenolanib targets KIT D816 in SM and CBF AML models: crenolanib inhibits cellular proliferation and initiates apoptosis of mastocytosis cell lines expressing these mutations." (PMID 29137311, 2017). "Both somatic and germline mutations of KIT have been described in GIST, mastocytosis and other cancers." (PMID 27777718, 2016). "Due to the fact that that pazopanib displays inhibitory effects on the KIT enzyme similar to those that have been used as off-label treatments, it poses an interesting alternative in the treatment of mastocytosis." (PMID 27196054, 2016). "Germline KIT mutations affect different tissues such as interstitial cells of Cajal (ICC), mast cells or melanocytes, and thereby lead to GIST, mastocytosis, or abnormal pigmentation." (PMID 27777718, 2016). "Here, we describe a new in vivo model of KIT D816V+ advanced systemic mastocytosis developed by transplantation of the human ROSAKIT D816V-Gluc mast cell line in NOD-SCID IL-2R g−/− mice, using Gaussia princeps luciferase as a reporter." (PMID 27783996, 2016). "KIT is a receptor tyrosine kinase that is implicated in gastrointestinal stromal tumor (GIST), mastocytosis and core binding factor (CBF) acute myeloid leukemia (AML)." (PMID 27777718, 2016). "Rare SNP on KIT exon 10 (A533D and F522C) are identified in systemic aggressive mastocytosis and lead to constitutive activation of the receptor." (PMID 26498480, 2015). "It will be interesting to elucidate the LIC containing fraction in the HSC pool that triggers KIT D814V induced mastocytosis, which subsequently can be targeted using PAK1 inhibitors." (PMID 26158763, 2015). "The proteasomal inhibitor MG132 up-regulates the expression of BIM and subsequently induces apoptosis in KIT D816V harboring cells, providing a strong rationale for using proteasomal inhibitors as a treatment option for mastocytosis." (PMID 26158763, 2015). "Taken together, these studies suggest that cooperation between KIT and TET2 mutations is likely to contribute to the pathogenesis of mastocytosis; the possibility that ASXL1 also plays a role in this process cannot be ruled out." (PMID 26158763, 2015). "It inhibits the activity of KIT in HMC mastocytosis cell line, and at pharmacological relevant concentrations against patient derived neoplastic MCs in vitro." (PMID 26158763, 2015). "In contrast, imatinib is poorly efficient as an inhibitor of KIT mutants D816V/H/Y/N found in mastocytosis." (PMID 25079768, 2014). "Imatinib, which inhibits KIT and several other tyrosine kinases, provides therapeutic benefits for some mastocytosis patients." (PMID 23185384, 2012). "Previous studies have established that reduced KIT expression, in conjunction with tyrosine kinase inhibitors, can decrease proliferation and increase apoptosis in the mastocytosis cell line HMC1.1, which carries the KITV560G activating mutation." (PMID 23185384, 2012).
mastocytosis (continued). "Recent studies have also shown the involvement of PI3K in abnormal KIT signaling due to activating KIT mutation (KITD816V in human and KITD814V in mouse), which causes hematologic malignancies including mastocytosis and mast cell leukemia." (PMID 22238586, 2012). "The stem cell factor receptor, KIT, is a target for the treatment of cancer, mastocytosis, and inflammatory diseases." (PMID 19789626, 2009). "In the last 15 years, activating mutations have been found in codon 816 of the tyrosine kinase KIT in children and adults with mastocytosis." (PMID 18509466, 2008). "For this reason, inhibitors of the KIT tyrosine kinase are being developed for the treatment of mastocytosis." (PMID 18509466, 2008). "Despite the high incidence of c-KIT kinase domain mutations in human patients with mastocytosis, only a total of 18 canine MCTs and 3 canine MCT cell lines have been evaluated for kinase domain mutations in c-KIT." (PMID 16579858, 2006). "The presence of detectable KIT mutations is not universal in mastocytosis cases, and the lack thereof does not exclude the possibility of a mastocytosis diagnosis." (PMID 40950415, 2025). "Neither patient met typical clinical findings of mastocytosis, which are maculopapular skin lesions, increased basal serum tryptase levels, activating D816V KIT mutation, insect venom anaphylaxis or unexplained osteoporosis." (PMID 40506943, 2025). "Mastocytosis is considered a nonhereditary somatic disease, with most cases presenting with a KIT point mutation in D816V." (PMID 40950415, 2025). "Additionally, expression of heterozygous KIT M541L has been primarily reported in patients with pediatric mastocytosis." (PMID 39037378, 2024). "Unlike adults, children with mastocytosis show the KIT p.D816V mutation in about 30% of skin biopsy cases, with other KIT-activating mutations in the extracellular domain present in about 40% of cases." (PMID 39456668, 2024). "Recently, some adults with mastocytosis are identified because of hymenoptera venom anaphylaxis, together with increased baseline serum tryptase levels or activating mutations in KIT, even without skin lesions." (PMID 38248039, 2024). "Patients with mastocytosis carrying the KIT M541L variant did not demonstrate significant differences in symptomatology compared to a matched reference cohort (n = 13/81) without KIT M541L." (PMID 39037378, 2024). "We then compared clinical symptoms and laboratory data on patients with systemic and cutaneous mastocytosis and bone marrow histopathology on a matched cohort with and without the KIT M541L variant." (PMID 39037378, 2024). "There were no typical skin lesions suggestive of mastocytosis, but a KIT D816V mutation was detected in the peripheral blood." (PMID 38132246, 2023). "A peripheral blood KIT D816V mutation analysis was negative, and she had no signs of skin lesions typical of mastocytosis." (PMID 38132246, 2023). "LADR cells were derived from CD34+ cells following the marrow aspiration of a patient with aggressive mastocytosis with no identified mutations in tyrosine-protein kinase (KIT)." (PMID 37569378, 2023). "Imatinib should be considered as a therapeutic option in the absence of a KIT D816V mutation, especially in the treatment of well differentiated bone marrow mastocytosis." (PMID 36694141, 2023). "A peripheral blood KIT D816V mutation analysis was negative, and he had no signs of cutaneous mastocytosis." (PMID 38132246, 2023). "Our search included terms such as ‘neonatal mastocytosis’, ‘infant mastocytosis’, ‘cutaneous mastocytosis’ + ‘infant and/or neonatal’, ‘Darier sign’, ‘c-kit’, ‘KIT gene mutations’, ‘CD117-positive cells’, ‘skin biopsy’, ‘bone marrow biopsy’, and ‘molecular genetic testing’." (PMID 38002964, 2023). "Generally, pediatric mastocytosis is not a hereditary disease associated with germline mutations of KIT." (PMID 38066824, 2023).
mastocytosis (continued). "It is worth mentioning that the correlation between KIT mutations in the skin and both the phenotype of childhood-onset mastocytosis and the clinical outcome is not clearly established." (PMID 38066824, 2023). "Somatic mutations that occur in KIT in the course of mastocytosis cause constitutive KIT activation even in the absence of SCF, which finally leads to the clonal proliferation of MCs in different organs." (PMID 37372988, 2023). "KIT appears to be a weak oncogene and could represent a late event in the pathogenesis of mastocytosis." (PMID 35745657, 2022). "Owing to the retrospective nature of our study, the KIT D816V mutation status was not known for all patients, preventing conclusions on its association with the subtype of paediatric mastocytosis." (PMID 35596520, 2022). "In this way, huMC‐derived KIT‐EVs may contribute to the pleiotropic clinical manifestations of mastocytosis, opening possibilities for investigating disease biomarkers." (PMID 36239715, 2022). "In contrast to adults with mastocytosis, the determination of the peripheral c-KIT mutation does not contribute to diagnosis and is therefore not necessary." (PMID 35028497, 2022). "Although KIT inhibitors present good inhibitory effects against MCs in vitro, treatment with KIT inhibitors alone has been disappointing in most published clinical trials for mastocytosis, likely due to the development of resistance against kinase inhibitors." (PMID 34063170, 2021). "It is also important to investigate whether TRK is required for KIT signaling to induce mastocytosis." (PMID 34063170, 2021). "KIT mutations are thought to be involved in the pathogenesis of the majority—if not all—variants of mastocytosis." (PMID 33401724, 2021). "The presence of activating KIT mutations alone is not sufficient to explain the different clinical forms of mastocytosis, suggesting that other inherited or somatic genetic variants are important in the regulation of MC proliferation and/or activation." (PMID 33401724, 2021). "Mastocytosis patients with HαT exhibited higher tryptase levels (independent of the MC burden), a significantly lower KIT D816V allele burden and more severe mediator-related symptoms than patients without HαT." (PMID 33671092, 2021). "Indeed, MITF expression is regulated by KIT-dependent signals and is required for the transformed phenotype of mastocytosis." (PMID 34066544, 2021). "Moreover, avapritinib is a recently identified KIT D816V inhibitor and shown to be useful for mastocytosis treatment." (PMID 32023940, 2020). "Therefore, since the emergence of tyrosine kinase inhibitors, KIT inhibition has been an attractive approach when facing mastocytosis treatment." (PMID 32346366, 2020). "The pivotal clinical study in mastocytosis that led to drug approval for this indication was a single-arm, phase 2 trial in 89 patients with ASM (n=16), SM-AHN (n=57) or MCL (n=16), mostly carrying the D816V KIT mutation." (PMID 32346366, 2020). "LAD2 cells were derived from CD34+ cells following marrow aspiration of a patient with aggressive mastocytosis where mutations in KIT were not identified." (PMID 31698677, 2019). "Similarly, phosphorylated AKT has been reported in the HMC-1 cell line (human KIT D816V+ leukemia MC line) which suggests the involvement of AKT activation in the pathogenesis of mastocytosis." (PMID 28725969, 2018). "In mastocytosis, somatic mutations of the coding Kit gene cause autocrine dysregulation and lead to constitutive KIT activation even in the absence of its ligand SCF." (PMID 28725969, 2018). "Thus, further studies are needed to investigate the role of MAPK/ERK and EGR3 in the pathogenesis of mastocytosis and the development of resistance to KIT inhibition in more details." (PMID 29088753, 2017). "This might explain at least in part why treatment with KIT inhibitors alone so far has been disappointing in most patients with mastocytosis." (PMID 29088753, 2017).